BTK (Bruton tyrosine kinase)
Diseases named in the same sentence as BTK in open-access papers (continued):
Sharing a sentence is not in itself a finding about the gene and the disease.
multiple myeloma (18 papers, 2013 to 2024). "In this Institutional Review Board approved protocol of Cleveland Clinic, we retrospectively evaluated the effects of BTK inhibitors ibrutinib and acalabrutinib therapy in patients (n = 4) with IgM-related AL amyloidosis due to underlying WM." (PMID 35096069, 2022). "We retrospectively evaluated the tolerability and effectiveness of BTK inhibitors ibrutinib and acalabrutinib therapy in (n = 4) patients with IgM-related AL amyloidosis with underlying WM." (PMID 35096069, 2022). "BTK inhibitors should be further investigated in larger prospective studies for treatment of AL amyloidosis in patients with lymphoplasmacytic lymphoma/WM." (PMID 35096069, 2022).
ovarian carcinoma (18 papers, 2015 to 2025). A malignant neoplasm originating from the surface ovarian epithelium. "This is the first report on the panorama gene profile of ovarian cancer metastasis to axillary lymph node and we found two novel mutations (BTK pD326E and EPHA5 pD251E)." (PMID 39925800, 2025). "While axillary lymph node metastasis from ovarian cancer is rare, our case represents the first report of BTK pD326E and EPHA5 pD251E mutations contributing to such metastasis." (PMID 39925800, 2025). "Ovarian cancer cells were found to express BTK, correlating with higher clinical disease stage, the risk for metastasis, and survival." (PMID 32532074, 2020). "Further research is needed to determine whether BTK inhibitors, already approved for B-cell malignancies, could provide a novel therapeutic approach for ovarian cancer patients harboring similar mutations." (PMID 39925800, 2025). "While BTK inhibitors such as ibrutinib have been developed primarily for hematologic malignancies, the presence of a BTK mutation in ovarian cancer could open avenues for novel off-label therapeutic strategies, especially if further studies support the role of BTK in solid tumor metastasis." (PMID 39925800, 2025). "For example, the BTK mutation’s role in kinase signaling suggests a need to explore off-label use of BTK inhibitors, traditionally used for hematologic malignancies, in solid tumors like ovarian cancer." (PMID 39925800, 2025). "Higher BTK expression increased metastasis and was related to cisplatin resistance through regulation of ovarian cancer stem cells." (PMID 34307353, 2021). "In human ovarian cancer tissues, the expression levels of BTK correlated with the stages of disease." (PMID 34307353, 2021). "CD83 highly-associated genes, such as ITGAM, IL1B, CYBB, PIK3R5, BTK, and OSM, ectopically express in ovarian cancer cells or tissues, involving in ovarian cancer progression, hypoxia networks, and the development of chemoresistance." (PMID 32823589, 2020). "It has been proposed that ovarian cancer stem cells play a role in cisplatin resistance and that BTK mediates chemoresistance through regulation of ovarian cancer stem cells." (PMID 29561760, 2018). "In ovarian cancer patients, increased BTK expression correlated with the presence of advanced stage disease and an increased chance of metastasis." (PMID 29561760, 2018). "Overall, the identification of BTK and EPHA5 mutations in this patient’s tumor highlights the expanding landscape of genetic drivers in ovarian cancer and underscores the potential for using precision medicine to address previously unidentified mutation- driven pathways." (PMID 39925800, 2025). "A longer follow-up would have provided a more robust assessment of the patient’s response to therapy and potential late-emerging resistance mechanisms, offering deeper insights into the prognostic implications of BTK and EPHA5 mutations in ovarian cancer metastasis." (PMID 39925800, 2025). "Another study has revealed that ovarian carcinoma cell proliferation and survival were significantly reduced by BTK inhibitors when tested both in vitro (using cell lines) and ex vivo (using cells newly dissociated from human xenografts and cancer cells originating from patients)." (PMID 36903645, 2023). "Furthermore, Ibrutinib decreased BTK phosphorylation and Sox2/Bcl-xL expression in ovarian cancer, diminishing their self-renewal capacities and proportion of cancer stem cells." (PMID 36145624, 2022). "In a recent publication, we revealed the oncogenic role of BTK in ovarian cancer and GBM." (PMID 34577576, 2021). "Likewise, ovarian cancer cells express BTK, and high expression levels are correlated with aggressiveness of disease, progression to Stage IV metastatic cancer, and poor survival." (PMID 33937249, 2021).
ovarian carcinoma (continued). "We discovered not only the common mutations including the tumor suppressive genes, metabolism-related genes, and DNA repair genes, but also the unique mutations in the BTK (D326E) and EPHA5 (D251E) genes adds further novelty, as these mutations have not been reported in ovarian cancer previously." (PMID 39925800, 2025). "In our study, the D326E of BTK mutation, located in the SH2 domain, suggests an altered function that could impact downstream B-cell receptor signaling pathways, which are not traditionally associated with ovarian cancer." (PMID 39925800, 2025).
Sepsis (18 papers, 2013 to 2025). Sepsis is defined as life-threatening organ dysfunction caused by a dysregulated host response to infection. "In line with the animal evidence, increased BTK expression in blood cells is associated with poor survival in patients with sepsis." (PMID 34778053, 2021). "Evidence obtained from Xid mice with an inactivating mutation of Btk verified that the protective effects of BTK inhibitors in polymicrobial sepsis are mediated solely by inhibition of BTK." (PMID 34778053, 2021). "Therefore, the results suggested that in the intestinal tissues of burn sepsis mice, the activation of BTK was closely associated with the activity of MPO." (PMID 35280898, 2022). "These aspects may explain how pseudomonas sepsis has become the most common presentation in patients with BTK mutations." (PMID 33013854, 2020). "Thus, our patient P1-1 had a [D521V] BTK missense mutation and presented with the Shanghai fever phenotype consisting of severe bloody diarrhea, neutropenia, eczema gangrenosum, and pseudomonas sepsis." (PMID 33013854, 2020). "Mechanically, we demonstrated that TREM2 interacted with the phosphatase SHP1 to inhibit bruton tyrosine kinase–mediated (BTK-mediated) FAO in sepsis." (PMID 39405126, 2024). "Meanwhile, the involvement of the SHP1/BTK axis in TREM2-mediated FAO regulation during sepsis was revealed." (PMID 39405126, 2024). "A study on pneumococcal pneumonia and sepsis suggested that BTK is critical for regulating myeloid cell-mediated innate host defense, particularly in neutrophils." (PMID 39518015, 2024). "To further clarify the influence of BTK on TREM2-mediated effects in vivo, we treated Lyz2Cre and TREM2fl/fl Lyz2Cre mice with ibrutinib and subsequently established a CLP sepsis model to investigate the potential role of BTK." (PMID 39405126, 2024). "This study aimed to investigate the role and molecular mechanisms of Bruton's tyrosine kinase (BTK), a member of the Tec family in burn sepsis-induced intestinal injury." (PMID 35280898, 2022). "Compared with those in the burn+sepsis group at the corresponding time points (8, 12, and 24 h), the expression levels of the p-BTK protein in the burn + sepsis + LFM-A13 group had significantly decreased." (PMID 35280898, 2022). "Then, we used LFM-A13 to intervene in mice to explore the roles and molecular mechanisms of BTK in burn-sepsis-induced intestinal injury." (PMID 35280898, 2022). "In the burn + sepsis group, the p-BTK expression level increased over time, peaked at 12, and then decreased at 24 h." (PMID 35280898, 2022). "Meanwhile, the Western blot analysis results indicated that the p-BTK level in the sham and burn groups were low, whereas that in the burn + sepsis group increased over time, peaked at 12 h, and then decreased at 24 h (P < 0.05)." (PMID 35280898, 2022). "Intestinal p-BTK expression in the burn+sepsis group was significantly increased compared with that in the sham and burn groups." (PMID 35280898, 2022). "Our previous study also showed that LFM-A13 inhibited BTK activation and inhibited the burn sepsis-induced pyroptosis of intestinal cells." (PMID 35280898, 2022). "Another study reported that BTK also made sense on lipopolysaccharide-induced sepsis and negatively regulated the lipopolysaccharide-induced canonical NF-κB signaling pathway in mast cells." (PMID 34136067, 2021). "In this study, we explored the activation of BTK in the intestinal tissue of burn sepsis mice." (PMID 35280898, 2022). "Inhibition of BTK activity with ibrutinib or acalabrutinib reduces both the activation of NF-κB in septic hearts and the cardiac dysfunction caused by cecal ligation and puncture (CLP)-sepsis." (PMID 35296647, 2022). "In addition, ITK and BTK regulate the thermal homeostasis in sepsis in mice through mast cell function." (PMID 33015708, 2020).
Sepsis (continued). "A one-year-old boy admitted for severe Staphylococcus aureus impetigo and sepsis was diagnosed with XLA (missense mutation of BTK gene 1706 G>C, R525P; absent expression of BTK protein from western blot analysis)." (PMID 23862092, 2013). "Together, these data demonstrate that phosphorylation of ADAP at Y571, mediated by BTK, is essential for sustaining the induction of PDPN in macrophages in response to LPS or in the context of sepsis." (PMID 39903516, 2025). "Eighty C57BL/6 mice were randomly divided into four groups: the sham group, the burn group, the burn + sepsis group, and the burn + sepsis + LFM-A13 (a selective BTK inhibitor) group." (PMID 35280898, 2022). "Another inhibitor of NLRP3 inflammasome activation identified in platelets is Ibrutinib, an inhibitor of Bruton’s tyrosine kinase (BTK), but its potential efficacy in sepsis has not yet been established." (PMID 37108623, 2023). "Bruton’s tyrosine kinase (BTK) plays a pivotal role in recruitment and function of immune cells and its inhibition was recently shown to improve renal function in experimental sepsis and lupus nephritis." (PMID 36911665, 2023). "Therefore, the selective blocking of BTK may provide greater benefits to patients than blocking the whole TLR4 pathway, and BTK may be an ideal target for intervention in patients under the condition of systemic inflammatory response and organ dysfunction caused by burn sepsis." (PMID 35280898, 2022). "Furthermore, TREM2-Fc treatment increased the phosphorylation of BTK in sorted monocytes from sepsis patients but not healthy donors." (PMID 39405126, 2024).
colon carcinoma (17 papers, 2016 to 2024). "We previously demonstrated that BTK is an actionable target in KRAS-mutated colon cancer." (PMID 31200752, 2019). "Finally, expression of BTK variants was found in cancer cells of breast, prostate and colon tumors." (PMID 27489860, 2016). "Recent studies have found that p65BTK is a new BTK subtype in Kirsten rat sarcoma virus oncogene-activated colon cancer and NSCLC." (PMID 37638060, 2023). "Recently we demonstrated that p65BTK, a new oncogenic isoform of BTK different from the already known 77 kDa isoform, is highly expressed in colon cancer cells and tissues." (PMID 31200752, 2019). "Recently, our lab identified and characterized p65BTK, a novel isoform of BTK, overexpressed in colon cancers." (PMID 31200752, 2019). "Preliminary data from our laboratory indicated that, unexpectedly, BTK is expressed in colon carcinoma cells, and thus we sought to define its function in colonic tissue." (PMID 26804170, 2016). "As alternative splicing of BTK mRNA has been reported in B-cell malignancies, we set out to identify the isoform expressed in colon cancers." (PMID 26804170, 2016). "By using isoform-specific siRNAs we confirmed that the BTK expressed in colon cancer cells is translated from exon 1b-containing mRNA and, because of its apparent molecular weight, we named it p65BTK." (PMID 26804170, 2016). "First, we observed that BTK is abundantly expressed in all colon cancer cell lines and tumour tissues analysed." (PMID 26804170, 2016). "Moreover, synergy of ibrutinib with immune checkpoint blockade has also been reported in mouse models of lymphoma, breast and colon cancer, but in a BTK-independent manner." (PMID 27489860, 2016). "We showed, that MM-129 exerts its favorable effect on colon cancer cells by inhibiting their crucial signaling pathways, such as PI3K/AKT/mTOR and Bruton’s tyrosine kinase (BTK), together with decreasing PD-L1 expression." (PMID 38201550, 2023). "MM-129 is a novel inhibitor targeting BTK/PI3K/AKT/mTOR and PD-L1, as it possesses antitumor activity against colon cancer." (PMID 34452183, 2021). "Findings from the literature data showed that BTK is aberrantly expressed in DLD-1 and HT-29 colon carcinoma cells and that LFM-A13 was able to decrease the phosphorylation of this kinase." (PMID 29690619, 2018). "Additionally, BTK-p65 level and its transforming potential seem to depend on the RAS/ERK/MAPK pathway in colon cancer and also in NSCLC." (PMID 36612306, 2023). "BTK is a member of the Tec family of nonreceptor protein tyrosine kinases which plays an important role in the development of B cell lymphoma and other solid tumors, including breast, ovarian, prostate and colon cancer." (PMID 34452183, 2021).
chronic graft versus host disease (16 papers, 2015 to 2026). Chronic graft versus host disease (GVHD) is a complication that can occur after a stem cell or bone marrow transplant in which the newly transplanted donor cells attack the transplant recipient's body. "BTK inhibitors offer an alternative to chemotherapy-based treatments for B-cell cancers or chronic graft-versus-host disease." (PMID 39728071, 2024). "For the treatment of chronic GVHD, Ibrutinib, an irreversible inhibitor of Bruton's tyrosine kinase (BTK), and Interleukin-2 inducible T-cell kinase (ITK), was recently granted FDA approval and is currently the only one approved for this purpose." (PMID 30211164, 2018). "Recently, novel key targets and signaling pathways have been identified in the pathogenesis of chronic GVHD, including Bruton’s tyrosine kinase (BTK), Janus kinases (JAKs), spleen tyrosine kinase (SYK), and many others." (PMID 28663793, 2017). "BTK inhibitors represent alternative agents to chemotherapy-based regimens and are indicated in patients with B-cell malignancies but also disorders such as chronic graft-versus-host disease." (PMID 38254833, 2024). "Ibrutinib is a first-in-class, once-daily covalent inhibitor of Bruton’s tyrosine kinase (BTK) approved for the treatment of various B-cell malignancies and chronic graft-versus-host disease following the failure of 1 or more lines of systemic therapy." (PMID 37296940, 2023). "By combining the agents ruxolitinib and ibrutinib, the hope is that not only will the response rate against chronic GVHD increase but also will the duration of involvement decrease by targeting GVHD from both the JAK and BTK pathways." (PMID 36258935, 2022). "Regarding BTK and ITK pathways, Ibrutinib, a BTK/ITK inhibitor, reduced the severity of chronic GVHD using two established chronic GVHD mice models." (PMID 34526990, 2021). "Previous studies have shown that Ibrutinib, an inhibitor of the related Tec kinase Bruton’s tyrosine kinase (BTK) which can also inhibit ITK, is able to reduce chronic GVHD." (PMID 33324410, 2020). "It is noteworthy that Ibrutinib, an inhibitor of BTK which can also inhibits ITK, is able to reduce chronic GVHD." (PMID 33324410, 2020). "In another study that investigated lncRNA expression in chronic graft-versus-host disease, three lncRNAs (NONHSAT142151, NONHSAT040475 and FR118417) were found to strongly correlate with the expression of mRNAs related to the BCR signaling pathway (BTK, CD72, DAPP1, LILRB3, NFKBIE, RASGRP3)." (PMID 39940921, 2025).
pancreatic cancer (15 papers, 2018 to 2025). "Whereas one study indicated an M2-skewing of BTK-deficient macrophages, recently in a pancreatic cancer mouse model an M1-skewing of intratumoral macrophages was found following ibrutinib treatment." (PMID 29455639, 2018). "In the context of pancreatic cancer, inhibition of Bruton's tyrosine kinase (BTK) disrupted B‐cell–macrophage interactions, restoring T‐cell responses and sensitising tumours to chemotherapy." (PMID 38997802, 2024). "Inhibition of BTK with ibrutinib enhances T cell-dependent antitumor immune responses and improves responsiveness of pancreas cancer to gemcitabine." (PMID 37064113, 2023). "They demonstrated that the pharmacological inhibition of BTK can activate adaptive immune responses in patients with pancreatic cancer, presenting a potential therapeutic regimen for treating this type of cancer." (PMID 34577576, 2021). "In another preclinical study in pancreatic cancer model, Bruton's tyrosine kinase (BTK) inhibitor ibrutinib repolarized macrophages into the M1 phenotype and promoted cytotoxic CD8+ T-cell activity." (PMID 30853982, 2019). "BTK has been validated as playing a critical role for mast cell degranulation in mouse models of pancreatic cancer (including insulinoma and PDAC)." (PMID 29561760, 2018). "Moreover, the BTK inhibitor ibrutinib improves survival in mouse models of pancreatic cancer, Therefore, the B-cell targeting approach may be beneficial for both pancreatitis and pancreatic cancer." (PMID 36969002, 2023). "We selected three important target genes (BTK, SYK and BRD4), and tested the anti-tumor effects of their inhibitors on pancreatic cancer cell lines." (PMID 40859234, 2025). "Glycofullerenes 66 and 67 induced autophagy and disrupted redox balance, triggering the upregulation of repair systems and disrupted Fyn and BTK protein levels in both pancreatic cancer cell lines, whilst being non-toxic for pancreatic cancer cells (PANC-1 and AsPC-1)." (PMID 36416290, 2022). "Bruton tyrosine kinase (BTK), a non-receptor enzyme in the Tec kinase family, is critical to maintain the desmoplastic microenvironment surrounded by an abundance of Tregs, MDSCs, TAMs and MCs in pancreatic cancer." (PMID 37064113, 2023).